INS (insulin)
Diseases named in the same sentence as INS in open-access papers (continued):
Sharing a sentence is not in itself a finding about the gene and the disease.
diabetes (continued). "Ventricular fibrillation is the most lethal arrhythmia and has the highest risk in poorly controlled chronic diabetics, the elderly, people receiving insulin therapy, and people with severe microvascular complications." (PMID 34692349, 2021). "In this study, we evaluate the algorithms used in OpenAPS/AndroidAPS and Loop, without meal announcements or user interactions, in a pig model of insulin‐deficient diabetes." (PMID 33931977, 2021). "MIDY is a form of early onset diabetes characterized by insulin deficiency in pancreatic β cells, caused by autosomal dominant mutations in the insulin (INS) gene." (PMID 34943844, 2021). "Diabetes mellitus is a metabolic disease characterized by high blood sugar caused by defective insulin secretion or impaired insulin action." (PMID 34471420, 2021). "Participants who had ever been treated with insulin (HR = 2.89, 2.30–3.62) and with longer duration of diabetes (p-value for trend <0.001) had a higher risk of RPC." (PMID 33444338, 2021). "Using this holistic multi-omics approach, we report marked adipose tissue depot-specific responses to insulin deficiency and chronic hyperglycemia, and provide new insights into the molecular pathology of insulin-deficient diabetes in adipose tissue depots." (PMID 34888323, 2021). "GCG, or the proglucagon gene, causes plasma glucose to rise in response to insulin-induced hypoglycemia and maintains the hyperglycemic condition in diabetes." (PMID 35154608, 2021). "Up-regulation of the double-stranded RNA-dependent protein kinase (PKR) causes impairment in insulin signaling pathway and metabolic dysfunctions in type 2 diabetes mellitus." (PMID 34155273, 2021). "Although different types of diabetes exist, all forms are attributable to two main causes: impaired insulin secretion and/or a reduced response of cells to the insulin action." (PMID 34681954, 2021). "Proposed mechanisms of the relationship between IGF1 and the risk of diabetes include IGF1 has the homology structure with insulin and is similar to insulin function that regulates hormones for insulin resistance and subsequently regulates glucose homeostasis." (PMID 34201855, 2021). "In summary, our studies showed that IRE1α RNase inhibitors STF and 4μ8c preserves β-cells and prevents the development of diabetes in insulin protein misfolding-causing Akita mice." (PMID 34675883, 2021). "The ultimate cause of diabetes mellitus is insufficient insulin production and secretion associated with reduced pancreatic β-cell mass." (PMID 34571886, 2021). "Rapamycin protects against AA induced nephropathy by activating the mTOR autophagy axis.The Usmg5, known as diabetes-associated protein in insulin-sensitive tissues (DAPIT), is a part of the mitochondrial ATP synthase." (PMID 34685389, 2021). "Such profile has been associated with insulin resistance and type 2 diabetes mellitus; arginase is regulated by insulin." (PMID 34248718, 2021). "Diabetes is a chronic disease caused by the inability of the pancreas to produce insulin or problems in the body to use it efficiently." (PMID 34450712, 2021). "These parameters are all suggestive of diabetes-induced retinal vessel dysfunction in the eLrrc8a KO mice, consistent with the loss of eNOS activity that is expected when insulin signaling is compromised." (PMID 33629656, 2021). "Diabetes is a metabolic disease that causes excess glucose in the blood (hyperglycemia), being represented by the deficiency of insulin secretion or insulin resistance." (PMID 34947271, 2021). "It showed that vitamin D improved insulin sensitivity and reduced the risk of prediabetes to diabetes progression." (PMID 34208589, 2021). "Here we sought to evaluate this aspect directly, by examining the long-term effects of increasing liver glycogen in an animal model of insulin-deficient and monogenic diabetes, namely the Akita mouse, which is characterized by reduced insulin production." (PMID 33667544, 2021).
diabetes (continued). "KEGG analysis also referenced metabolic and insulin pathways, which is in agreement with genetic, clinical and experimental studies that have linked Tnmd to metabolic syndrome, diabetes and obesity." (PMID 34741033, 2021). "The main cause of CFRD is insulin insufficiency with insulin secretion being increasingly impaired in correlation with exacerbation of pre-diabetes." (PMID 34017312, 2021). "Diabetes mellitus is a metabolic disorder characterized by hyperglycemia caused due to defects in insulin production, insulin sensitivity, or both." (PMID 34257624, 2021). "On the other hand, the pathogenesis of type 2 diabetes mellitus (DM2) is essentially linked to the development of a state of resistance to the actions of insulin." (PMID 34830663, 2021). "Type 2 diabetes originates in various sites including adipose tissue which becomes insulin resistant caused by alterations in the insulin signaling pathway, and so it is important to understand the pathway that directly impacts diabetes." (PMID 34225729, 2021). "Here, the authors identify the WFS1 protein, which is mutated in Wolfram syndrome and associated with diabetes, as an ER to Golgi cargo receptor required for normal insulin processing and secretion." (PMID 34848728, 2021). "Non-diabetic (NOD) mice spontaneously develop autoimmune diabetes and represent many features of human T1D including a T1D-susceptible MHC allele (I-Ag7), homologous to HLA-DQ8, the development of insulin autoantibodies prior to diabetes onset, and insulitis." (PMID 34868047, 2021). "Research associates rs7903146 with a higher risk of gestational and type 2 diabetes as well as reduced insulin levels." (PMID 33849843, 2021). "Chronic dysregulation of glucagon and insulin signaling underlie the pathogenesis of type 2 diabetes mellitus T2DM, and the activities of both hormones must be studied together." (PMID 33708137, 2021). "A declining PN introduces the risk of incorrect folding of insulin’s precursor, preproinsulin, which can lead to diabetes." (PMID 35058801, 2021). "This classification focused on pathogenesis, separating diabetes resulting from absolute insulin deficiency, typically secondary to autoimmunity, or from progressive loss of insulin secretion in the setting of insulin resistance." (PMID 33828529, 2021). "iPSCs have been successfully used to create human models of diabetes caused by monogenic disorders that effect beta cell development and function such as Wolfram syndrome and insulin gene mutations." (PMID 33868170, 2021). "Diabetes mellitus (DM), a highly prevalent disease worldwide, is caused by insufficient insulin production or insulin resistance." (PMID 34276388, 2021). "Early prediction of insulin sensitivity in young adults and effective intervention can be a critical factor in terms of delaying or preventing diabetes in normoglycemic individuals who are at risk of diabetes." (PMID 34900785, 2021). "β-cell death is regarded as a major event driving loss of insulin secretion and hyperglycemia in both type 1 and type 2 diabetes mellitus." (PMID 34822454, 2021). "Type 2 diabetes mellitus (T2DM) occurs when there is a progressive loss of insulin secretion combined with insulin resistance." (PMID 34805411, 2021). "In pancreas ß-islet cells, HNF1A contributes to insulin secretion in response to glucose and is associated with maturity-onset diabetes of the young-like diabetes." (PMID 34493690, 2021). "Diabetes is a metabolic disease resulting from a deficiency in insulin secretion and insulin function." (PMID 34249256, 2021). "This is a retrospective report of the frequency of severe hypoglycemia and the association between common mental disorders and type 1 diabetes mellitus treated with insulin analogues." (PMID 33320451, 2021). "Diabetes is a metabolic disorder that causes a lack or resistance to insulin, which is a hormone critical for the regulation of blood sugar levels." (PMID 34035925, 2021).
diabetes (continued). "Diet enriched in transfat intake has been associated with diabetes, insulin sensitivity and systemic inflammation." (PMID 34680405, 2021). "After this switch, the United Kingdom Prospective Diabetes Study 82 risk equations predicted events based on co-existing risk factors and treatment intensification to basal bolus insulin were applied." (PMID 34348729, 2021). "At the time of clinical onset, the diabetes rats in the saline, His42, and delayed diabetes groups exhibited substantial loss of beta cells with the remaining insulin+ cells accounting for 7 ± 8% of the islet cells." (PMID 33815287, 2021). "This study aimed to find different patterns of FPIS in subjects with normal glucose tolerance (NGT) and analyzed the relationship between insulin secretion patterns and the risk for development of type 2 diabetes mellitus (T2DM)." (PMID 34867781, 2021). "Studies in mice and humans indicate that insulin deficiency in diabetes decreases mitochondrial respiration, ATP production and downregulates the mitochondrial genes and proteins, which is prevented with the treatment of insulin." (PMID 35185597, 2021). "In patients with diabetes, the large fluctuation in BGLs has been associated with several complications, and the use of glucose-responsive insulin delivery systems is an important means to maintain blood glucose homeostasis." (PMID 35056918, 2021). "In conclusion, our results support (a) greater loss of beta cell function in younger diabetes onset; (b) persistent insulin secretion, particularly with later diabetes onset and longer duration; and (c) relationships of C-peptide levels with circulating miRs." (PMID 34083567, 2021). "It promotes diabetes onset and aggravates this disorder and its associated complications by disrupting insulin release and action." (PMID 34956587, 2021). "The pathogenesis of low bone density in type 1 diabetes mellitus (T1DM) is related to decreased peak bone mass because of deficiency in insulin and insulin-like growth factors, leading to slow osteoblast growth and poor collagen synthesis." (PMID 33849514, 2021). "Diabetes (diabetes mellitus, DM) is a metabolic disease that is characterised by high blood glucose, which is caused by dysfunction in insulin secretion and/or insulin resistance." (PMID 34176494, 2021). "The ability of IRS to get activated and transmit downstream signals is diminished in insulin-responsive tissues, leading to impaired insulin secretion and insulin dysfunction, which are major causes of diabetes." (PMID 34489627, 2021). "Conceivably, in pathological conditions such as diabetes wherein cells are insensitive to insulin, patients become increasingly susceptible to infections because macrophages will be inefficient in eliminating pathogens as a result of reduced glycolysis." (PMID 34555129, 2021). "Type 1 Diabetes mellitus (T1DM), which constitutes ~5–10% of diabetes cases, has a high incidence in children and adolescents and is caused by the destruction of the insulin producing β-islets in the pancreas." (PMID 34884494, 2021). "Many studies have indicated that blood urea nitrogen is associated with increased an risk of insulin use in diabetes mellitus." (PMID 33850659, 2021). "Diabetes can accelerate the loss of muscle mass and strength due principally to insulin resistance, levels of inflammatory cytokines, and associated changes in endocrine function." (PMID 34959843, 2021). "Islet transplantation, for instance, has been considered for many years as a solution for diabetes reversal, following the loss of insulin producing BCM." (PMID 34944640, 2021). "Diabetes is caused by abnormal glucose levels or inappropriate tolerance, accompanied by an insufficient insulin response." (PMID 34168187, 2021).
diabetes (continued). "Diabetes mellitus (DM), a diverse endocrine illness signified by hyperglycemia, is caused by a deficiency in insulin production, insulin activity, or both." (PMID 34527070, 2021). "According to American Diabetes Association, diabetes is a metabolic change characterized by the presence de hyperglycemia caused by a deficiency and/or malfunctioning of insulin secretion." (PMID 33597978, 2021). "Aerobic physical activity has been shown to favour weight loss and improvements of insulin sensitivity and glucose metabolism in obesity and type 2 diabetes mellitus." (PMID 34831711, 2021). "Diabetes mellitus is characterized by elevated levels of blood glucose and is ultimately caused by insufficient insulin production from pancreatic beta cells." (PMID 33828531, 2021). "The monogenic diabetes subclass was additionally divided into monogenic defects of β-cell function, monogenic defects in insulin action and other genetic syndromes associated with diabetes." (PMID 34299172, 2021). "According to the current World Health Organization (WHO) definition, diabetes mellitus (DM) is a group of metabolic disorders characterized by the presence of hyperglycaemia caused by impaired release or function of insulin." (PMID 33670143, 2021). "An increasing patient risk factor for anaphylaxis comprise diabetes mellitus treatment with protamine-containing insulin and allergic responses to fish proteins." (PMID 34200384, 2021). "Decreased insulin secretion, associated with pancreatic β-cell failure, plays a critical role in many human diseases including diabetes, obesity, and cancer." (PMID 34439408, 2021). "Exacerbation of STZ-induced diabetes in Prlr null mice was associated with reduced islet density, number of β-cells, insulin expression, and circulating insulin levels." (PMID 33746901, 2021). "Type 1 diabetes mellitus (T1DM) is an autoimmune metabolic diseases associated with deficient insulin secretion and resulting in impaired carbohydrate metabolism (dysglycemia; Galassetti and Riddell, 2013)." (PMID 33897473, 2021). "Mechanistically, because glucose entry into the cardiomyocyte is largely dependent on insulin action, a fasting- or diabetes-induced reduction in insulin causes a rise in the intracellular AMP-to-ATP ratio, with a resultant activation of AMPK." (PMID 34356640, 2021). "This shows that adding HDL-cholesterol to the clustering allows the identification of a separate group among those with mild diabetes with very low risk of glycaemic deterioration towards insulin requirement." (PMID 34110439, 2021). "We therefore aimed to investigate the effect of oral Mg supplementation on glucose and insulin-sensitivity parameters in participants with diabetes or at high risk of diabetes, compared with a placebo." (PMID 34836329, 2021). "One differential volumetric analysis of pancreatic islets revealed a β-cell deficit in adults with diabetes that was associated with increased maximal blood glucose, suggesting that β-cell loss leads to reduced insulin production in T2D." (PMID 34822454, 2021). "Type 1 diabetes mellitus (T1DM) is an autoimmune disease resulting from loss of insulin-secreting β-cells in islets of Langerhans." (PMID 35115945, 2021). "It has been reported that DHEA-S can up-regulate the expression of ACC1, and promote insulin secretion, which had a useful therapeutic effect on diabetes mellitus, especially for patients with insulin secretion deficiency." (PMID 34771066, 2021). "Diabetes is characterized by chronic hyperglycemia caused by defects in the insulin secretion or action pathway." (PMID 34944640, 2021). "The resulting steatosis impairs insulin signaling, contributing to insulin resistance and increasing the risk of developing type 2 diabetes mellitus." (PMID 36090909, 2021). "Surprisingly,leptin significantly reduced blood glucose in mouse models of insulin-deficient diabetes, suggesting that leptin modulated glucose homeostasis independently of insulin." (PMID 34446063, 2021).
diabetes (continued). "Loss of pancreatic insulin-secreting β-cells due to metabolic or autoimmune damage leads to the development of diabetes." (PMID 34340653, 2021). "This study detected an interaction of diabetes duration with insulin use to be associated with hypertension among people with T2DM." (PMID 34424924, 2021). "These toxic products increase with diabetes severity and cause deleterious modifications to proteins, lipids, and DNA—inducing inflammation and insulin resistance, and impairing insulin secretion." (PMID 34333586, 2021). "With chronic hyperglycemia, there is a perpetually high demand for insulin, and β-cells eventually become exhausted, resulting in insufficient insulin synthesis and secretion causing overt diabetes." (PMID 34673835, 2021). "Diabetes mellitus is a metabolic disorder with chronic high blood glucose levels, and it is associated with defects in insulin secretion, insulin resistance, or both." (PMID 34925525, 2021). "Serum vitamin D status exerts effects on glucose-insulin-homeostatic states underlying Diabetes-Mellitus, Type 2 (T2DM)." (PMID 33602978, 2021). "T2DM is characterized by an initial stage of insulin resistance or prediabetes, caused by the inability of the cells to fully respond to insulin, associated with blood glucose levels above the normal range but below the diabetes diagnostic threshold." (PMID 33578998, 2021). "Diabetes mellitus (DM) represents a group of chronic, metabolic diseases, with the main feature of chronic hyperglycemia caused by defects in insulin secretion, insulin efficacy, or, most often, both." (PMID 34451910, 2021). "It was the first-ever anti-diabetic drug with the mechanism of insulin sensitization, carrying the belief of reducing cardiovascular risks associated with diabetes upon addressing the primary metabolic defect." (PMID 34631571, 2021). "From a physiological perspective, processes underlying pre-diabetes and T2D are a continuum that is initiated by resistance to insulin action in mediating glucose transport in peripheral organs, such as the liver, skeletal muscle and AT." (PMID 34071774, 2021). "We used mice with a mutation in the leptin receptor gene (db/db), which leads to insulin resistance in the early stage of T2DM, and deficiency of insulin secretion in the late stage of diabetes." (PMID 33916828, 2021). "Downregulation or disruption of GLUT4 was able to cause insulin tolerance, which further leads to severe diabetes and obesity." (PMID 34174964, 2021). "Because it is an important complication of diabetes, its association with changes in insulin levels and insulin resistance, the causative factors of diabetes, has attracted widespread attention." (PMID 34366917, 2021). "While coding and non-coding genetic variants linked to diabetes often impact mechanisms regulating insulin secretion from beta cells, some of them perturb the development of the pancreas, islets, and beta cells themselves." (PMID 33828531, 2021). "Diabetes is a metabolic disorder caused by impaired insulin secretion or insulin action bringing the improper balance of glucose homeostasis." (PMID 33803588, 2021). "Type 2 diabetes mellitus (T2DM) is caused by a progressive loss of β-cell insulin secretion on the background of insulin resistance." (PMID 34167465, 2021). "Type 2 diabetes mellitus is a complex and chronic metabolic disease caused by a combination of insulin resistance and an ineffective insulin secretory response." (PMID 33800583, 2021). "Diabetic mellitus (DM) is the most communal metabolic disease resulting from a defect in insulin secretion, causing hyperglycemia by promoting the progressive destruction of pancreatic β cells." (PMID 34641920, 2021). "For instance, STZ-induced diabetes in rodents is oftentimes used in preclinical studies to model human T1D since it recapitulates loss of insulin-producing β-cells and basic pathophysiology in human T1D." (PMID 33478120, 2021).